KLLN (killin, p53 regulated DNA replication inhibitor)
Description:
Has the ability to inhibit DNA synthesis and S phase arrest coupled to apoptosis. Has affinity to both double- and single-stranded DNA.
Synonyms: killin; CWS4
Tractability: No criterion of Open Targets' tractability assessment is met for any kind of drug.
Gene: Protein-coding gene on chromosome 10 (87,859,158 to 87,863,533, reverse strand). Ensembl gene ENSG00000227268.
Subcellular location: Nucleus
Subcellular location (Human Protein Atlas): Nucleoplasm; Nucleoli
Gene Ontology:
Cellular component: nucleolus; nucleoplasm; nucleus
Genetic constraint (gnomAD): Loss-of-function variants: 0 observed, 0.85 expected, observed/expected ratio (o/e) 0, 90% interval 0 to 1.76. That is too few expected variants to judge how well the gene tolerates losing a copy. Missense variants: 340 observed, 241.19 expected, observed/expected ratio (o/e) 1.41, 90% interval 1.29 to 1.54. Synonymous variants: 142 observed, 101.9 expected, observed/expected ratio (o/e) 1.39, 90% interval 1.22 to 1.6.
Homologues: Orthologues: chimpanzee KLLN (99% identical), macaque KLLN (84% identical).
Diseases named in the same sentence as KLLN in open-access papers:
KLLN is named in the same sentence as 25 diseases in open-access papers, as found by Europe PMC text mining. Sharing a sentence is not in itself a finding about the gene and the disease. The quoted sentences say what the papers report.
breast carcinoma (9 papers, 2012 to 2025). "Somatic KLLN deletions were found in 21% of breast carcinomas in The Cancer Genome Atlas (TCGA), and decreased KLLN expression is associated with increased tumor grade in breast carcinomas vs. adjacent normal tissue." (PMID 30245854, 2018). "Recent studies show that KLLN has a tumor supressor effect and is associated with worse prognosis in prostate and breast carcinomas." (PMID 25679508, 2015). "In addition, KLLN gene deletions are linked to high risk for thyroid and breast cancer." (PMID 29308088, 2018). "Immunoblotting and immunofluorescence showed that the addition of leptomycin B increased the nuclear fraction of KLLN at both 4 h and 16 h post-treatment in colon and breast cancer cell lines." (PMID 33400740, 2020). "KLLN overexpression in colon and breast cancer cells showed both nuclear and cytoplasmic presence." (PMID 33400740, 2020). "Evidence supporting somatic KLLN deletions have also been observed in 21% of breast carcinomas in The Cancer Genome Atlas (TCGA) and there has been an established association between increased tumor grade and decreased KLLN expression in breast carcinomas versus adjacent normal tissue." (PMID 33400740, 2020). "In PTEN mutation negative CS/CSL, KLLN germline promoter hypermethylation is observed in up to 35% of patients and is associated with three-fold increased prevalence of breast carcinomas and two-fold increased prevalence of renal cell carcinomas." (PMID 33400740, 2020). "To assess if KLLN nuclear sequestration affected cell viability or cell proliferation, we performed live cell counts and MTT assays, respectively, in all our colon and breast cancer cells." (PMID 33400740, 2020). "Besides, KLLN expression showed negative correlation with miR-3940-3p expression in the breast cancer samples." (PMID 36123344, 2022).
Cowden syndrome (5 papers, 2018 to 2024). "Hypermethylation of the KLLN promoter is potentially causative for Cowden syndrome, which includes an increased risk for breast and colorectal cancer." (PMID 34711244, 2021). "Germline promoter hypermethylation of KLLN is associated with a cancer-predisposition syndrome, Cowden syndrome." (PMID 30245854, 2018). "In a study including 91 patients with clinical manifestations compatible with Cowden syndrome but without constitutional PTEN, SDHx mutations, or KLLN hypermethylation, referred to as CLS, germline mutations in the PIK3CA gene were found in eight individuals and two in the AKT gene." (PMID 39336800, 2024).
prostate carcinoma (5 papers, 2018 to 2024). A carcinoma that arises from epithelial cells of the prostate gland.
melanoma (3 papers, 2023 to 2025). A malignant, usually aggressive tumor composed of atypical, neoplastic melanocytes. "By binding to the ARE in the 3′-UTR of KLLN mRNA, KSRP promotes KLLN mRNA decay, and this interaction has been positively correlated with cell growth and proliferation in melanoma." (PMID 40699755, 2025). "One such mechanism that has been identified through which KSRP modulates melanoma cell growth is the regulation of KLLN expression by RNA–protein interaction." (PMID 40699755, 2025). "This demonstrates that targeting KSRP’s ability to suppress the tumor suppressor KLLN can have potential therapeutic effects in regulating melanoma growth." (PMID 40872475, 2025). "Thus, it is likely that KLLN plays a role in promoting the significant reduction in melanoma cell migration, colony formation, and proliferation, while also contributing to the increase in apoptosis that we observed in this study." (PMID 40699755, 2025). "And finally, in melanoma, by binding to the ARE in the 3′-UTR of KLLN mRNA, KSRP has been observed to promote KLLN mRNA decay, resulting in increased cell growth and proliferation." (PMID 40699755, 2025). "Knock down (KD) of KSRP has been shown to increase KLLN expression and inhibit melanoma cell growth, while the overexpression of KSRP has demonstrated the opposite effect and decreased KLLN expression, restoring melanoma cell growth." (PMID 40699755, 2025). "Given the clinical significance of PTEN, but not the alternative target gene ATAD1 and KLLN, as well as the evidence of direct interaction between E_156 and the PTEN promoter in melanoma, we evaluated the tumor-suppressive function of E_156 in vitro." (PMID 37904237, 2023).
renal cell carcinoma (3 papers, 2020 to 2025). "To gather more evidence towards KLLN involvement in protein degradation, we used computational analysis of publicly available data from TCGA using the UALCAN web resource and observed that in renal cell carcinomas, KLLN, TRIM25 and MDM2 gene expression are positively correlated with each other." (PMID 33400740, 2020).
colorectal cancer (2 papers, 2021 to 2022). A primary or metastatic malignant neoplasm that affects the colon or rectum. "When analyzing large rearrangements, we found several cases in which the deletion also affected other genes, such as KLLN, a neighbor gene of PTEN, but also BMPR1A, a further upstream gene associated with juvenile polyposis syndrome (JPS; MIM 174,900) and colorectal cancer risk." (PMID 35227301, 2022).
glioma (2 papers, 2012 to 2024). A benign or malignant brain and spinal cord tumor that arises from glial cells (astrocytes, oligodendrocytes, ependymal cells). "In addition, CCK8 results showed that overexpression of PTEN or KLLN in U251 and U118 cells resulted in a decrease in cell proliferation, suggesting that PTEN and KLLN also affect glioma cell viability." (PMID 38725030, 2024). "In addition, the target gene TCF12 is highly expressed in glioma and acts as a transcription factor to control the transcription of LINC00606, PTEN, and KLLN." (PMID 38725030, 2024).
colon cancer (1 paper, 2020). "To empirically confirm the computational data, we used plasmid-based transfection of GFP and FLAG-tagged KLLN plasmids followed by immunoblotting to show that KLLN localizes to both the nucleus and cytoplasm in breast and colon cancer cell lines." (PMID 33400740, 2020). "Immunofluorescence after GFP-tagged KLLN transfection confirmed that KLLN does localize to both the nucleus and cytoplasm in breast and colon cancer cell lines." (PMID 33400740, 2020). "The 2008 KLLN discovery study suggested that KLLN was exclusively localized in the nucleus based on plasmid-based transfection and immunofluorescence in one colon cancer cell line." (PMID 33400740, 2020). "These researchers drew this conclusion based on results observed after transfection of a GFP-tagged KLLN plasmid in one colon cancer cell line." (PMID 33400740, 2020). "The subcellular localization of KLLN as a nuclear protein that tends to concentrate in the nucleolar region was established in the discovery study observing overexpressing GFP-tagged KLLN in the colon cancer cell line HCT116." (PMID 33400740, 2020). "Using ImageJ densitometric analysis, we showed that in colon cancer cell line HCT116, there was a two-fold increase in nuclear retention of the KLLN L73_78F mutant protein." (PMID 33400740, 2020).
epithelial dysplasia (1 paper, 2022). "In addition, methylation of KLLN, CHFR, TP73, GSTP1, and CASP8 may be related to precancerous processes, such as epithelial hyperplasia and epithelial dysplasia." (PMID 35681626, 2022).
glioblastoma (1 paper, 2015). The most malignant astrocytic tumor (WHO grade IV). "Consequently, the loss of KLLN that is observed in 88% of the glioblastoma samples would help the development of tumor cells by decreasing apoptosis and favoring proliferation." (PMID 25679508, 2015).
non-small cell lung carcinoma (1 paper, 2023). A group of at least three distinct histological types of lung cancer, including non-small cell squamous cell carcinoma, adenocarcinoma, and large cell carcinoma.
oral cancer (1 paper, 2022). "We found that a combination of six genes (TP73, CASP8, RARB, KLLN, GSTP1, and CHFR) could distinguish oral cancer from clinically diagnosed OPMDs with high diagnostic performance (area under the curve [AUC], 0.885; sensitivity, 77.8%; and specificity, 87.1%)." (PMID 35681626, 2022). "Evaluation of the combination of six genes with aberrant methylation (RARB, KLLN, CHFR, TP73, GSTP1, and CASP8) was particularly useful for identifying early-stage oral cancer in clinically diagnosed patients with OPMDs with high diagnostic performance." (PMID 35681626, 2022).
osteosarcoma (1 paper, 2017). A usually aggressive malignant bone-forming mesenchymal neoplasm, predominantly affecting adolescents and young adults. "Osteosarcomas carrying H3F3A G34W/R mutations are associated with epigenetic dysregulation of KLLN/PTEN and HIST1H2BB." (PMID 28484590, 2017). "Specifically, we found that the promoter region of the genes HIST1H2BB (p < 0.00005) and KLLN/PTEN (p < 0.0005) showed significantly higher methylation levels in H3F3A G34 mutant osteosarcomas." (PMID 28484590, 2017). "The most differentially methylated promoters between H3F3A G34W/R mutant and H3.3 wild-type osteosarcomas were in KLLN/PTEN (p < 0.00005) and HIST1H2BB (p < 0.0005)." (PMID 28484590, 2017).
pancreatic ductal adenocarcinoma (1 paper, 2024). An infiltrating adenocarcinoma that arises from the epithelial cells of the pancreas. "Combining analyses of RNA‐seq and ChIP‐seq data, the authors further identify killin (KLLN) as a transcriptional target of KMT2D and EBF2 in pancreatic ductal adenocarcinoma (PDAC) cells." (PMID 38015024, 2024).
psoriasis (1 paper, 2025). An autoimmune condition characterized by red, well-delineated plaques with silvery scales that are usually on the extensor surfaces and scalp. "Up-regulated miR-744-3p in psoriasis regulated the proliferation and differentiation of keratinocytes by targeting KLLN." (PMID 40861221, 2025).
renal carcinoma (1 paper, 2022). A carcinoma arising from the epithelium of the renal parenchyma or the renal pelvis. "The only distinctive clinical feature of the patients with KLLN and PTEN overexpression was an increased presence of renal cancer." (PMID 35227301, 2022).
triple-negative breast carcinoma (1 paper, 2025). An invasive breast carcinoma which is negative for expression of estrogen receptor (ER), progesterone receptor (PR), and human epidermal growth factor receptor 2 (HER2). "Similarly, in triple-negative breast cancer, the SEMA3B-AS1 plays a role as a decoy for miR-3940-3p to inhibit the degradation of its target gene KLLN." (PMID 40225417, 2025).
tumor (16 papers, 2015 to 2025). "Decreased KLLN expression results in tumor cell advancement, including potential resistance to BRAF inhibitors." (PMID 40872475, 2025). "Tumor-suppressor genes, including APC, BARD1, HMMR (RHAMM), KLLN, LZTR1, MCPH1 (BRIT1), MLH1, NF1, RB1CC1 (FIP200), SLC22A18, and SPTBN1, have been found to increase the risk of disease and tumor development." (PMID 40941673, 2025). "Knockdown of KLLN markedly attenuated the tumor‐suppressive phenotype of GSK‐LSD1 in SW1990 and PANC‐1 cells." (PMID 38015024, 2024). "PTEN and KLLN can participate in the inhibition of tumor development and the regulation of cancer progression." (PMID 38725030, 2024). "Mechanistically, RNA immunoprecipitation (RIP) and luciferase reporter assays confirmed that lncRNA SEMA3B-AS1 acted as sponge for miR-3940-3p, preventing the degradation of its target gene KLLN, which acts as a tumor-inhibiter in TNBC." (PMID 36123344, 2022). "KLLN has many identified tumor suppressor functions, and when first reported, was thought to be exclusively nuclear." (PMID 33400740, 2020). "We and others have also shown previously that KLLN regulates cellular viability and cell proliferation, thereby affirming its role as a tumor suppressor protein." (PMID 33400740, 2020). "Factors, for example, tumour suppresser gene, KLLN, can also regulate H3K9me3 by altering SUV39H1 activity through interaction with DBC127." (PMID 28779172, 2017). "KLLN overexpression reduces PCa cell growth in vitro by decreasing the androgen receptor (AR) signaling, while its repression increases it; this is consistent with a tumor suppressor function of this gene." (PMID 30009155, 2018). "Hence, this study demonstrated that KLLN was a tumor suppressor in TNBC cells." (PMID 36123344, 2022). "IHC staining exhibited that KLLN was also significantly downregulated in PDAC tissues, and its expression was negatively correlated with tumor stage, lymph node metastasis, and distal metastasis in PDAC patients." (PMID 38015024, 2024). "PTEN is a tumor suppressor downstream of the PI3K signaling pathway, while KLLN inhibits DNA synthesis and induces apoptosis." (PMID 38725030, 2024). "The KLLN gene localizes to 10q23 and shares a transcription start site with PTEN, also a tumor suppressor gene." (PMID 33400740, 2020). "Rescue experiments were also performed to testify whether the tumor suppressive effect of KMT2D and EBF2 is mediated by KLLN." (PMID 38015024, 2024). "For each cancer type, we searched for matching gene expression and copy number datasets of at least three patients carrying homozygous deletions of these four genes (PAPSS2, ATAD1, KLLN, and PTEN) without considering other factors, such as tumor grade, age, or gender of the patients." (PMID 37984988, 2024).
cancer (6 papers, 2012 to 2024). A tumor composed of atypical neoplastic, often pleomorphic cells that invade other tissues. "Since renal cell carcinoma is a component cancer of Cowden syndrome and KLLN is a known cancer predisposition marker for CS/CSL patients, we used the renal cell carcinoma data as a surrogate to identify the KLLN-TRIM25-MDM2 axis in the regulation of protein degradation." (PMID 33400740, 2020). "Therefore, KLLN could broadly contribute to both cancer susceptibility and sporadic carcinogenesis." (PMID 33400740, 2020). "However, for the same two cancers, when a pathway analysis was run on the shared list of genes whose expression correlates positively with KLLN and TRIM25, the protein ubiquitination pathway was observed to be the top canonical pathway." (PMID 33400740, 2020). "This suggests lack of KLLN could be involved in both cancer susceptibility and sporadic carcinogenesis." (PMID 30245854, 2018). "Using COBRA we found that the KLLN gene body (region 1), as well as the KLLN and PTEN TSS (region 3) were completely unmethylated in all 36 cancer cell lines analysed." (PMID 22490388, 2012). "First, we inspected gene aberrations of the PAPSS2, ATAD1, KLLN, and PTEN loci in 26 cancer types." (PMID 37984988, 2024). "Here, we report on KLLN’s role in DNA damage response (DDR) mediated through apoptosis in breast cells with and without a cancer phenotype." (PMID 30245854, 2018).
KLLN also shares sentences with these, for which no sentence is quoted: ovarian carcinoma (2 papers); colitis (1); hamartoma (1); juvenile polyposis syndrome (1); Pancreatic Cancer (1); thyroid (1).